GPX4 (glutathione peroxidase 4)
Diseases named in the same sentence as GPX4 in open-access papers (continued):
Sharing a sentence is not in itself a finding about the gene and the disease.
cholangiocarcinoma (13 papers, 2022 to 2025). A carcinoma that arises from the intrahepatic biliary tree (intrahepatic cholangiocarcinoma) or from the junction, or adjacent to the junction, of the right and left hepatic ducts (hilar cholangiocarcinoma). "The investigators speculated whether NCOA4 is involved in the development of cholangiocarcinoma through the mechanism underlying GPX4-mediated iron-dependent cell death." (PMID 40788949, 2025). "In this study, the expression of NCOA4 and GPX4 in cholangiocarcinoma cells confirmed the presence of iron-mediated cell death in cholangiocarcinoma cells and its involvement in cellular regulation." (PMID 40788949, 2025). "The carbonylation of HSP70 and α1-AT degrades GPX4 and promotes iron-mediated cell death, which leads to the progression and poor prognosis of cholangiocarcinoma." (PMID 40788949, 2025). "The experimental results of this study illustrate that NCOA4 knockdown increases GPX4 expression, inhibits iron-mediated cell death, and promotes the malignant behavior of cholangiocarcinoma cells." (PMID 40788949, 2025). "Additionally, IDH1 is involved in cholangiocarcinoma by inducing the GPX4-regulated ferroptosis pathway." (PMID 38536014, 2024). "Inhibiting ferroptosis by regulating the phosphatase and tensin homolog/solute carrier family 7 member 11/glutathione peroxidase 4 axis, thereby promoting cholangiocarcinoma (CCA) proliferation and migration." (PMID 39314046, 2024). "In cholangiocarcinoma (CCA), vitamin E, similar to ferroptosis inducers such as RSL3 and erastin, can directly inhibit GPX4 and lead to the accumulation of lipid peroxides, collectively inducing ferroptosis in cancer cells, thereby effectively suppressing tumor development." (PMID 41614790, 2025).
male infertility (13 papers, 2005 to 2025). The inability of the male to effect fertilization of an ovum after a specified period of unprotected intercourse. "Meanwhile, Fujii and Imai (2014) described GPX4 as playing an essential role in spermatogenesis, and therefore male infertility, by identifying that mitochondrial GPX4 variants determine structural abnormalities in the central part of the sperm." (PMID 38790168, 2024). "A defect in GPX4 has been suspected as a cause of male infertility triggered by Se deficiency, although direct evidence for its requirement is missing." (PMID 16137335, 2005). "A strong positive correlation between Gpx4 mRNA levels and sperm motility was observed, suggesting that reduced GPX4 expression may be a key factor in the ferroptosis mechanism underlying male infertility." (PMID 40331931, 2025). "Gpx4 is important for normal spermatozoa development, as it protects sperm cells from oxidative stress and is a necessary structural protein in mature spermatozoa, and Gpx4 expression alterations are associated with male infertility." (PMID 33861392, 2021). "In busulfan-induced oligospermia models, Fer-1 restored sperm quality by upregulating Gpx4 and modulating Nrf2 signaling, underscoring its therapeutic potential in male infertility." (PMID 40331931, 2025). "Differently, the spermatocyte-specific deletion of GPX4 results in oligoasthenozoospermia and male infertility, but this is mainly because GPX4 functions as a structural protein of the mitochondrial capsule rather than an antioxidant enzyme in spermatozoa." (PMID 38790639, 2024). "Studies have shown treatment of germ cells with selenium can increase GPX4 expression, maintain spermatozoal motility, and increase germ cell proliferation, indicating the xCT/GPX4 system plays a role in male infertility." (PMID 37770442, 2023). "Both the conditional knockout of Gpx4 in spermatocytes and the deletion of its mitochondrial form of Gpx4 (mGpx4) lead to male infertility due to severe structural defects of sperm with irregular mitochondrial alignment and swollen mitochondria." (PMID 32050598, 2020). "There is a certain organic correlation among ferroptosis, the GPX4 activity, and male infertility." (PMID 36672785, 2022). "A correlation between male infertility and a GPX4 defect has actually been reported." (PMID 16137335, 2005). "Additionally, hepatitis infections can cause sperm defects, and exposure to hepatitis B surface antigens can downregulate GPX4 expression in Sertoli cells, indicating that hepatitis may induce male infertility via ferroptosis in Sertoli cells." (PMID 40331931, 2025). "Consequently, when considering the inhibition of ferroptosis as a treatment for male infertility, we should attach great importance to the Cyst(e)ine/GSH/GPX4 axis." (PMID 36672785, 2022). "Among the family of GPXs, the activity of GPX1-4 is dependent on selenium, of which GPX4 is an important structural protein that is very abundant in sperm mitochondria (about 50% of sperm mid-segment proteins), while when it is absent it leads to male infertility." (PMID 37174590, 2023).
clear cell renal cell carcinoma (12 papers, 2022 to 2025). "KLF2 and GPX4 expression have been found to be negatively correlated, which can cause ferroptosis in renal clear cell carcinoma by regulating GPX4 transcription." (PMID 40969276, 2025). "For example, it has been demonstrated that Krüppel-like factor 2 regulates ferroptosis through GPX4, hence preventing cancer cell migration and invasion in clear cell renal cell carcinoma." (PMID 37488128, 2023). "When the ferroptosis inhibitor is added after inhibiting GPX4 in renal clear-cell carcinoma, cell death is decreased because HIF inhibits GPX4 to cause ferroptosis." (PMID 37598126, 2023). "kruppellike factor 2 directly inhibits GPX4 gene transcription, consequently reduces GPX4 levels and promotes ferroptosis in clear cell renal cell carcinoma." (PMID 36289191, 2022). "Moreover, the knockdown of tribbles pseudokinase 3 triggers ferroptosis via the SLC7A11/GPX4 pathway, enhancing sunitinib efficacy in clear cell renal cell carcinoma." (PMID 39935430, 2025). "Finally, in clear cell renal cell carcinoma, KLF2 deficiency inhibits ferroptosis by impairing GPX4 transcriptional repression, promoting tumor migration and invasion." (PMID 38495481, 2024). "Previous studies have predicted that the immune checkpoint molecule programmed death-1 is positively correlated with the expression level of ACSL4 but negatively correlated with the expression levels of GPX4 and HSPB1 in clear cell renal cell carcinoma." (PMID 37488128, 2023). "In clear cell renal cell carcinoma, the DHODH inhibitor selectively inhibited tumor growth in GPX4-low tumors, while combined treatment with sulfasalazine, which also induces ferroptosis, synergistically inhibited the growth of GPX4-high tumors." (PMID 37842232, 2023).
esophageal squamous cell carcinoma (12 papers, 2021 to 2026). Esophageal squamous cell carcinoma (ESCC) is a type of esophageal carcinoma (EC) that can affect any part of the esophagus, but is usually located in the upper or middle third. "This study investigated the prognostic significance and clinical associations of FSP1 and GPX4 expression in esophageal squamous cell carcinoma (ESCC) and assessed the therapeutic potential of regulating these molecules in ESCC cells." (PMID 36576648, 2023). "Together, these data indicate that targeting Hsp27 or GPX4 to block this intrinsic protective mechanism against ferroptosis is a potential treatment strategy for eradicating CSC in esophageal squamous cell carcinoma." (PMID 35053196, 2021). "The lncRNA TMEM44-AS1, for instance, can inhibit ferroptosis and stabilize GPX4 mRNA, thus promoting the malignant growth of esophageal squamous cell carcinoma (ESCC) by binding to the RNA-binding protein IGF2BP2." (PMID 40271153, 2025). "A study explored the impact of DNAJB6a in esophageal squamous cell carcinoma (ESCC), emphasizing its association with cancer-related processes, ferroptosis, AKT signaling, and GPX4." (PMID 38562143, 2024). "In a study of esophageal squamous cell carcinoma, treatment with 5-ALA led to the inhibition of glutathione peroxidase 4 (GPX4), a crucial antioxidant enzyme, and upregulation of HO-1 expression in the cells." (PMID 41476774, 2026). "In esophageal squamous-cell carcinoma (ESCC), the expression of GPX4 was downregulated by the knockdown of aurora kinase A (AURKA), which led to the activation of ferroptosis and suppression of cancer progression." (PMID 39125992, 2024). "Recent studies have shown that high GPX4 expression levels and low HMOX1 expression levels are poor prognostic factors for patients with esophageal squamous cell carcinoma." (PMID 35562364, 2022). "For example, 5-ALA induces ferroptosis via regulation of GPX4 and heme oxygenase 1 (HMOX1) and exerts antitumor effects in esophageal squamous cell carcinoma cell lines and BALB/cAJcl-nu/nu mice with subcutaneously transplanted KYSE30 cells." (PMID 35562364, 2022). "They found that increasing the levels of GPX4 might counteract the effects of TMEM44-AS1 elimination, hence promoting the growth, movement, and penetration of esophageal squamous cell carcinoma (ESCC) cells via ferroptosis." (PMID 39036600, 2024).
hemorrhagic stroke (12 papers, 2020 to 2025). A stroke caused by a bleed on the brain. "Particularly, in a hemorrhagic stroke model, the intraperitoneal injection of a single dose of Se upregulated the expression of Sp1 and GPX4, promoting the recovery of neurological function and reducing the size of cerebral infarction." (PMID 40873639, 2025). "A recent study showed that selenium treatment promoted GPx4 expression and inhibited ferroptosis in hemorrhagic stroke models." (PMID 36184790, 2022). "In mice, GPx4 knockdown causes age-related neurodegenerative changes and neuronal loss.In addition, promoting the expression of the lipid antioxidant GPx4 prevents neuronal damage in a hemorrhagic stroke model." (PMID 36234847, 2022). "Pharmacological selenium inhibits GPX4-dependent ferroptotic death, and selenome protects neurons and improves behavior following hemorrhagic stroke through regulating TFAP2c and Sp1." (PMID 35264947, 2021). "Ferroptosis also induced neuronal death after hemorrhagic stroke 185 and a single dose of Se delivered into the brain could drive the expression of GPX4, protect neurons, and improve behavior in a hemorrhagic stroke model." (PMID 33204324, 2020). "Because GPX4 is a selenoprotein, pharmacological selenium (Se) delivered into the brain augments GPX4 expression, and this effect inhibits ferroptotic death as well as cell death induced by excitotoxicity or ER stress to protect neurons and improve behavior in a hemorrhagic stroke model." (PMID 33294126, 2020). "In addition, several agents upregulating GPX4, including selenium (Se), dauricine, baicalin, crocin, and curcumin (CUR), have shown beneficial effects after the occurrence of hemorrhagic stroke." (PMID 38992073, 2024).
Hepatic steatosis (12 papers, 2021 to 2026). Steatosis is a term used to denote lipid accumulation within hepatocytes. "Gpx4‐deficient mice exhibited lower levels of systemic inflammation, reduced adipocyte hypertrophy, and diminished hepatic steatosis." (PMID 41524084, 2026). "Taken together, these findings suggest that macrophage‐specific Gpx4 deficiency alleviates HFD‐induced hepatic steatosis, potentially through enhanced fatty acid degradation and transport." (PMID 41524084, 2026). "siRNA-induced knockdown of GPX4 resulted in reduced lipid stress, ferroptosis, and cell damage, all of which are linked to the progression of metabolic-associated fatty liver disease." (PMID 39989969, 2025). "In the present study, our results found that FFAs-induced hepatic steatosis was associated with concurrent accumulations of iron and ROS, lipid peroxidation, and mitochondrial damage, alongside a reduction in GPX4 expression." (PMID 38397738, 2024). "For instance, inhibiting GPX4 activity induces ferroptosis in HCC cells; targeting GPX4 can mitigate ferroptosis to treat metabolic-associated fatty liver disease." (PMID 38515187, 2024). "BMP4 suppresses markers of hepatic steatosis, inflammation, and liver injury by upregulating glutathione peroxidase 4 (GPX4), thereby reducing ferroptosis." (PMID 40243151, 2025). "Our results showed that RSL-3 treatment effectively abrogates the protective effects of NaB on FFA-induced hepatic steatosis, and disrupts its influence on GPX4-mediated ferroptosis pathways." (PMID 38397738, 2024). "In the present study, our results showed that NaB mitigates hepatic steatosis by lowering ROS and intracellular iron levels, which in turn modulates GPX4-mediated ferroptosis and subsequently reduces lipid accumulation." (PMID 38397738, 2024). "EGCG alleviates liver damage, lipid accumulation, oxidative stress, and hepatic steatosis, increases NRF2 and GPX4 expression in iron-overloaded mice, and enhances antioxidant capacity." (PMID 41050396, 2025).
Hyperglycemia (12 papers, 2022 to 2025). An increased concentration of glucose in the blood. "GPX4 lentivirus restored downregulated GPX4 expression caused by hyperglycemia in corpus cavernosum." (PMID 36290619, 2022). "Moreover, our data showed that hyperglycemia caused changes in ferroptosis-related markers, including GPX4, ACSL4, iron, and MDA levels, in diabetic rats." (PMID 36290619, 2022). "In diabetic retinopathy models, ferrostatin-1 (Fer-1) alleviated hyperglycemia-induced suppression of the GSH/GPX4 axis, thereby restoring redox homeostasis in retinal cells." (PMID 40276370, 2025). "In diabetic wounds, hyperglycemia and metabolic disturbances exacerbate oxidative stress, impairing the function of the Nrf2/GPX4 pathway and thereby promoting ferroptosis, which delays wound healing." (PMID 40969904, 2025). "The intracellular GPX4 reduction in hyperglycemia environments then leads to an overabundance of ROS and Fe2+ in various cells, including ECs." (PMID 38645427, 2024). "Collectively, these results unveil the Syvn1/Nrf2/GPx4 pathway as a critical mediator of the protective effects of H2S against ferroptosis and apoptosis induced by hyperglycemia and hyperlipidemia in cardiomyocytes." (PMID 37875467, 2023). "In our current work, both total and intercellular ROS in hRECs were elevated, and the expression of GPX4 was significantly compromised under hyperglycemia, indicating the highly oxidative environment in endothelial cells under HG." (PMID 36092160, 2022). "Immunofluorescence results demonstrate that the number of both endothelial cells and smooth muscle cells were decreased under the circumstance of hyperglycemia, whereas GPX4-LV injection protected their survival in diabetic rats." (PMID 36290619, 2022). "Hyperglycemia is hypothesized to induce myocardial lipid peroxidation via mitochondrial iron overload and suppression of glutathione peroxidase 4 (GPX4) activity, leading to impaired myocardial contractile function." (PMID 40538809, 2025). "It has been reported by other studies that hyperglycemia could reduce GPX4 expression by inactivating the Nrf2/GPX4 pathway or facilitating GPX4 ubiquitination by TRIM46." (PMID 36290619, 2022). "Hyperglycemia may promote TRIM46-mediated GPX4 ubiquitination, thereby lowering the expression of GPX4 in retinal capillary ECs, leading to more EC ferroptosis." (PMID 38645427, 2024).
inflammatory bowel disease (12 papers, 2012 to 2026). A spectrum of small and large bowel inflammatory diseases of unknown etiology. "GPX4 deficiency in the pancreas or small intestine can lead to pancreatitis and inflammatory bowel disease." (PMID 38515187, 2024). "Supporting the data presented here, GPX1 and GPX4 selenoprotein gene loci have been implicated in GWAS of inflammatory bowel disease (IBD), which is a risk factor for CRC development." (PMID 31027226, 2019). "In humans, fourteen genes affecting oxidative stress, including GPX1 and GPX4, are candidate genes for inflammatory bowel disease (IBD) and oxidative stress has been associated with IBD." (PMID 22970191, 2012). "Additionally, Gpx4‐deficient mice fed with PUFAs develop enteritis resembling Crohn's disease, underscoring the role of ferroptosis in inflammatory bowel disease pathogenesis." (PMID 39568772, 2024). "Conversely, the activation of GPX4 has been shown to alleviate inflammation, enhance intestinal barrier function, and reduce oxidative stress in inflammatory bowel disease." (PMID 40565780, 2025). "In Inflammatory Bowel Disease (IBD), ferroptosis of intestinal epithelial cells caused by dysfunctional GPx4 and heightened ACSL4 protein level damages the mucosal barrier." (PMID 41462611, 2025). "In inflammatory bowel disease, ferroptosis is notably elevated in intestinal epithelial cells in both ulcerative colitis and Crohn's disease, accompanied by reduced GPX4 activity." (PMID 39568772, 2024). "Previous studies have shown that iron deposition, glutathione depletion, glutathione peroxidase 4 (GPX4) inactivation, and lipid peroxidation are the basic characteristics of iron death in the damaged gastrointestinal tract of patients with inflammatory bowel disease." (PMID 40084946, 2025).